ARID5A (AT-rich interaction domain 5A)
Description:
DNA-binding protein that may regulate transcription and act as a repressor by binding to AT-rich stretches in the promoter region of target genes. May positively regulate chondrocyte-specific transcription such as of COL2A1 in collaboration with SOX9 and positively regulate histone H3 acetylation at chondrocyte-specific genes. May stimulate early-stage chondrocyte differentiation and inhibit later stage differention (By similarity). Can repress ESR1-mediated transcriptional activation; proposed to act as corepressor for selective nuclear hormone receptors. As an RNA-binding protein, involved in the regulation of inflammatory response by stabilizing selective inflammation-related mRNAs, such as STAT3 and TBX21 (By similarity). Also stabilizes IL6 mRNA. Binds to stem loop structures located in the 3'UTRs of IL6, STAT3 and TBX21 mRNAs; at least for STAT3 prevents binding of ZC3H12A to the mRNA stem loop structure thus inhibiting its degradation activity. Contributes to elevated IL6 levels possibly implicated in autoimmunity processes. IL6-dependent stabilization of STAT3 mRNA may promote differentiation of naive CD4+ T-cells into T-helper Th17 cells. In CD4+ T-cells may also inhibit RORC-induced Th17 cell differentiation independently of IL6 signaling. Stabilization of TBX21 mRNA contributes to elevated interferon-gamma secretion in Th1 cells possibly implicated in the establishment of septic shock (By similarity). Stabilizes TNFRSF4/OX40 mRNA by binding to the conserved stem loop structure in its 3'UTR; thereby competing with the mRNA-destabilizing functions of RC3H1 and endoribonuclease ZC3H12A (By similarity).
Synonyms: MRF-1; MRF1; RP11-363D14
Tractability: PROTAC: UniProt records ubiquitination sites on it; ubiquitination databases record sites on it.
Gene: Protein-coding gene on chromosome 2 (96,536,717 to 96,552,638, forward strand). Ensembl gene ENSG00000196843.
Subcellular location: Nucleus
Subcellular location (Human Protein Atlas): Nucleoplasm; Nucleoli
Gene Ontology:
Molecular function: identical protein binding; mRNA 3'-UTR AU-rich region binding; nuclear androgen receptor binding; nuclear estrogen receptor binding; nuclear retinoid X receptor binding; nuclear thyroid hormone receptor binding; protein binding; sequence-specific DNA binding; transcription corepressor activity; transcription factor binding; DNA binding; transcription cis-regulatory region binding; chromatin binding; RNA stem-loop binding
Biological process: cellular response to estrogen stimulus; negative regulation of transcription by RNA polymerase II; positive regulation of 3'-UTR-mediated mRNA stabilization; negative regulation of DNA-templated transcription; regulation of transcription by RNA polymerase II; cellular response to lipopolysaccharide; positive regulation of interleukin-17 production; positive regulation of interleukin-6 production; positive regulation of T-helper 1 cell cytokine production; positive regulation of T-helper 17 type immune response; positive regulation of tumor necrosis factor production; positive regulation of type II interferon production
Cellular component: nucleolus; nucleoplasm; nucleus; transcription regulator complex
Genetic constraint (gnomAD): Loss-of-function variants: 14 observed, 27.28 expected, observed/expected ratio (o/e) 0.51, 90% interval 0.34 to 0.8. The upper end of that interval is the gene's LOEUF score, 0.8, which puts it in group 3 of 6, group 1 being the genes least tolerant of losing a copy. Missense variants: 669 observed, 748.37 expected, observed/expected ratio (o/e) 0.89, 90% interval 0.84 to 0.95. Synonymous variants: 338 observed, 321.23 expected, observed/expected ratio (o/e) 1.05, 90% interval 0.96 to 1.15.
Homologues: Orthologues: chimpanzee ARID5A (99% identical), macaque ARID5A (97% identical), pig ARID5A (84% identical), mouse Arid5a (77% identical), rat Arid5a (76% identical), dog ARID5A (73% identical), rabbit ARID5A (69% identical), guinea pig ARID5A (68% identical), Drosophila melanogaster htk (24% identical), Caenorhabditis elegans arid-1 (10% identical). Paralogues in human: ARID5B (33% identical), ARID4B (18% identical), ARID4A (16% identical).
Diseases named in the same sentence as ARID5A in open-access papers:
ARID5A is named in the same sentence as 30 diseases in open-access papers, as found by Europe PMC text mining. Sharing a sentence is not in itself a finding about the gene and the disease. The quoted sentences say what the papers report.
lung carcinoma (6 papers, 2020 to 2023). "In contrast, low expression of Arid5a was associated with poor prognosis of lung cancer in a previous study." (PMID 35126382, 2021). "In contrast, low expression of ARID5A in lung cancer is associated with poor prognosis." (PMID 34094918, 2021). "β-catenin also mediates the activation of FOS-like antigen 2 (FOSL2) and repression of the AT-rich interaction domain 5A (ARID5A) driving TAMs to switch from M1-like to M2-like in lung cancer." (PMID 37759870, 2023). "The research found that ARID5A regulates the inflammatory process, low expression of which is correlated with poor prognosis of lung cancer patients." (PMID 36034939, 2022). "Thus far, few studies have investigated the tumoral role of ARID5A; one study reported that ARID5A is related to the prognosis of lung cancer patients, where patients with high expression of ARID5A have a better prognosis." (PMID 34094918, 2021). "Furthermore, high expression of β-catenin and Fosl2 and low expression of Arid5a were found in a transcriptome analysis of lung cancer cases and were correlated with poor prognosis." (PMID 35126382, 2021).
rheumatoid arthritis (6 papers, 2020 to 2026). A chronic, systemic autoimmune disorder characterized by inflammation in the synovial membranes and articular surfaces. "Increased Arid5a levels in the CD4+ T-cells of untreated rheumatoid arthritis (RA) patients are reduced by the anti-IL-6 receptor antibody tocilizumab, implicating the contribution of the IL-6-ARID5A axis in RA pathogenesis." (PMID 39682280, 2024). "We highlight six tocilizumab responsive genes (ARID5A, BCL3, PIM1, SOCS3, BATF, MYC) that are associated with IL-6 pathway and known to be perturbed by tocilizumab treatment in rheumatoid arthritis patients." (PMID 35064122, 2022). "However, several studies have demonstrated the involvement of transcription factors expressed in chondrocytes, such as AT-rich interactive domain 5a (Arid5a), Arid5b, and IκBζ, in rheumatoid arthritis." (PMID 32079226, 2020). "Although the involvement of Arid5a in pathogenesis of rheumatoid arthritis is still unknown, it might be an important transcription factor during onset." (PMID 32079226, 2020). "Notably, in untreated rheumatoid arthritis (RA) patients, the expression of ARID5a in CD4+ T cells is enhanced, whereas treatment with the anti-IL6R antibody tocilizumab results in a decrease in the expression of Arid5a, indicating that the IL-6-ARID5A axis may be involved in the pathogenesis of RA." (PMID 36010693, 2022). "Importantly, in untreated rheumatoid arthritis (RA) patients, expression of Arid5a in CD4+ T cells is increased, whereas treatment with the anti-IL-6 receptor antibody tocilizumab is associated with decreased Arid5a expression, indicating that the IL-6-ARID5a axis may be involved in RA pathogenesis." (PMID 36408139, 2022).
autoimmune disease (5 papers, 2019 to 2024). A disorder resulting from loss of function or tissue destruction of an organ or multiple organs, arising from humoral or cellular immune responses of the individual to their own tissue constituents. "The association of Arid5a with inflammation and autoimmune diseases and a variety of cancers has been revealed." (PMID 35126382, 2021). "However, little is known regarding the manner in which Arid5a regulates mRNAs post-transcriptionally and whether is associated with the development of inflammatory and autoimmune diseases or cancer." (PMID 35126382, 2021). "Mice lacking Arid5a show weakened responses to LPS, with the reduced expression of Il6 and Ifnγ, and the resistance to lethal endotoxic shock, indicating the role of Arid5a in enhancing Th1 and Th17 cell functions in inflammation and autoimmune diseases." (PMID 39682280, 2024). "Meanwhile, ARID5A has been shown to mainly regulate inflammatory and autoimmune disease development by regulating the expression of Interleukin-6 (IL-6) mRNA." (PMID 36755810, 2023). "Arid5a is indispensable in the development of inflammatory and autoimmune diseases, such as experimental autoimmune encephalomyelitis (EAE), sepsis, RA, acute lung injury (ALI), as well as breast, lung, pancreatic (PDAC), colorectal (CRC), and brain cancers." (PMID 35126382, 2021). "This demonstrates the dual function of the Arid5a protein to bind both DNA and RNA to facilitate the pathogenesis of inflammatory and autoimmune diseases and cancer." (PMID 35126382, 2021). "Accordingly, strategies to inhibit expression of these stimuli can aid in indirectly suppressing Arid5a expression and be posed as alternate treatment options for IL-6-dependent inflammatory and autoimmune diseases." (PMID 31867000, 2019). "Interestingly, a decade ago the family member Arid5a was found to bind and stabilize mRNAs of immune system key players and thereby account for driving inflammatory and autoimmune diseases." (PMID 37129704, 2023). "Overall, Arid5a plays important roles in promoting inflammation and autoimmune diseases." (PMID 31867000, 2019). "Indeed, by stabilizing mRNAs of several inflammatory molecules, Arid5a has been shown to regulate the development of inflammatory and autoimmune diseases." (PMID 31867000, 2019).
Autoimmunity (3 papers, 2022 to 2024). The occurrence of an immune reaction against the organism's own cells or tissues. "In addition, a prior study demonstrated that targeting the phosphorylation and degradation of Arid5a could facilitate the release of IL-6, consequently exerting a critical role in autoimmunity." (PMID 35725649, 2022).
experimental autoimmune encephalomyelitis (3 papers, 2019 to 2022). An autoimmune demyelinating disease of the central nervous system that is produced experimentally in animals by the injection of homogenized brain or spinal cord in Freund's adjuvant. "Moreover, a prior study indicated that down-regulation of Arid5a led to diminished levels of IL-6 in LPS-treated mice, and further prevented development of experimental autoimmune encephalomyelitis." (PMID 35725649, 2022). "Due to its ability to bind to these regions, the novel function of Arid5a in mRNA stability was first identified when it was found to bind to the Il-6 3′UTR in the cytoplasm, promoting the production of IL-6 in vivo and inducing experimental autoimmune encephalomyelitis (EAE)." (PMID 31867000, 2019).
glioma (3 papers, 2021 to 2022). A benign or malignant brain and spinal cord tumor that arises from glial cells (astrocytes, oligodendrocytes, ependymal cells). "In this study, to understand the potential role of ARID5A in glioma, we investigated the diagnostic and prognostic significance of ARID5A in glioma by data mining in the Chinese Glioma Genome Atlas (CGGA) and The Cancer Genome Atlas (TCGA) datasets." (PMID 34094918, 2021). "A recent study determined the diagnostic and prognostic significance of Arid5a in gliomas and discovered a possible biological function for Arid5a." (PMID 35126382, 2021). "Our results indicate that the expression of ARID5A is probably associated with immune functions in glioma." (PMID 34094918, 2021). "The expression of ARID5A in glioma is associated with poor prognosis of glioma patients, and ARID5A expression in glioma is related to patient age, IDH mutation status, and 1p/19q co-deletion." (PMID 34094918, 2021). "Deep research of the expression and function of ARID5A in glioma can provide accurate diagnostic evidence and reliable prognostic information, and thus improve the clinical therapeutic level of glioma." (PMID 34094918, 2021). "Therefore, the potential role of ARID5A in glioma and its underlying mechanism are required for further experimental study." (PMID 34094918, 2021). "Furthermore, we also found that the expression of ARID5A was negatively associated with tumor purity in glioma, suggesting that ARID5A expression also is negatively associated with prognosis." (PMID 34094918, 2021). "ROC curve analysis proved that the ARID5A expression level has diagnostic value for gliomas." (PMID 34094918, 2021). "High expression of ARID5A is associated with poor prognosis in glioma." (PMID 34094918, 2021). "We analyzed the correlation between ARID5A expression and WHO grade, age, IDH mutation,1p/19q co-deletion in glioma patients based on CGGA and TCGA RNA sequencing data and clinical and molecular characterization data." (PMID 34094918, 2021). "have recently reported upregulation of Arid5a in glioma is positively correlated with inflammation, immune response, IFNγ-mediated signaling, and apoptosis which affect the proliferation and growth of cancer cells." (PMID 35126382, 2021). "Subsequently, gene ontology (GO) analysis and gene set enrichment analysis (GSEA) were used to detect the possible biological functions and pathways of ARID5A in glioma." (PMID 34094918, 2021). "Subsequently, the relationship between ARID5A expression and the clinical characteristics of glioma patients was evaluated using the Chinese Glioma Genome Atlas (CGGA) database and The Cancer Genome Atlas (TCGA) database." (PMID 34094918, 2021). "The prognosis of patients with high ARID5A expression was significantly poorer than that of patients with low ARID5A expression, indicating that high expression of ARID5A is probably a marker of poor prognosis in glioma." (PMID 34094918, 2021). "We used the TIMER online analysis tool to study the correlation between ARID5A expression in glioma and the level of immune infiltration." (PMID 34094918, 2021). "From the results above, we can conclude that ARID5A is correlated with immune infiltration in glioma." (PMID 34094918, 2021). "GO analysis revealed that co-expression genes of ARID5A are significantly involved in some important functions in glioma, and GSEA showed that multiple cancer-associated and immune-associated signaling pathways are enriched in the high ARID5A expression group." (PMID 34094918, 2021). "ARID5A expression was significantly higher in IDH-wildtype gliomas than in IDH mutant gliomas, and the difference was statistically significant (P < 0.001)." (PMID 34094918, 2021). "The prognostic value of ARID5A in glioma was estimated by Kaplan-Meier analysis and the receiver operating characteristic (ROC) curve analysis." (PMID 34094918, 2021).
glioma (continued). "The Tumor Immune Estimation Resource (TIMER) database was used to analyze the relationship between ARID5A and immune cell infiltration in glioma." (PMID 34094918, 2021). "We then used the Tumor Immune Estimation Resource (TIMER) database to assess the relationship between ARID5A and tumor-infiltrating immune cells (TIICs) in glioma." (PMID 34094918, 2021). "ARID5A is also a prognostic biomarker for glioma, which is correlated with immune infiltration." (PMID 36034939, 2022). "Next, ARID5A expression was compared between IDH-wildtype and IDH-mutation gliomas." (PMID 34094918, 2021). "TIMER database indicated that ARID5A is correlated with tumor-infiltrating immune cells in glioma." (PMID 34094918, 2021). "Interestingly, recent studies have reported a role for Arid5a in many cancers including glioma, breast, pancreatic, lung, and colorectal cancer." (PMID 35126382, 2021). "We found that ARID5A may be a prognostic and molecular target for glioma, which can help guide the treatment selection of glioma patients." (PMID 34094918, 2021). "In conclusion, our study discovered the biological function of ARID5A in glioma for the first time." (PMID 34094918, 2021). "Furthermore, we investigated the correlation between the expression of ARID5A and the clinical and molecular characteristics of glioma patients." (PMID 34094918, 2021). "We combined the RNA sequencing data from GTEx and TCGA databases to analyze the differences in ARID5A expression between normal and glioma tissues, including 1152 normal brain tissues from the GTEx database, five normal brain tissues and 697 glioma tissues from the TCGA database." (PMID 34094918, 2021). "Collectively, these findings indicate that ARID5A may be a potential prognostic biomarker and is correlated with immune infiltration in glioma." (PMID 34094918, 2021). "A gene ontology analysis suggested a correlation of inflammatory response, immune response, and IFNγ-mediated signaling pathway with higher Arid5a expression in glioma, which may further reveal mechanisms that affect the growth, and proliferation of cancer cells." (PMID 35126382, 2021). "In addition, ARID5A plays an important role in inflammation and immunity; we also found that ARID5A may play a vital role in regulating the immune microenvironment of glioma and thus affect the progression of glioma." (PMID 34094918, 2021). "Moreover, high expression of Arid5a is likely a marker of poor prognosis in glioma." (PMID 35126382, 2021). "Therefore, ARID5A can be used as a promising molecular predictor to evaluate the prognosis of glioma patients as well as a therapeutic target in the clinical detection of glioma." (PMID 34094918, 2021). "However, the role of Arid5a in glioma has been primarily based on database mining; therefore, comprehensive studies utilizing cell culture, animal models, and/or patient samples is needed to confirm a regulatory function of Arid5a in glioma." (PMID 35126382, 2021). "Studying the function of ARID5A in glioma and its immune microenvironment will be helpful for us to better understand this cancer and could result in the identification of a new gene-targeted immunotherapy in glioma." (PMID 34094918, 2021). "Low grade gliomas and GBM datasets were analyzed using online database, such as TCGA, and inversely correlated high expression of Arid5a with the prognosis of all stages of gliomas." (PMID 35126382, 2021).